MIR26A2 (microRNA 26a-2)
Synonyms: hsa-mir-26a-2; MIRN26A2; mir-26a-2
Gene: MicroRNA gene on chromosome 12 (57,824,609 to 57,824,692, reverse strand). Ensembl gene ENSG00000207789.
Gene Ontology:
Biological process: miRNA-mediated post-transcriptional gene silencing
Cellular component: RISC complex
Homologues: Orthologues: chimpanzee ptr-mir-26a-2 (100% identical), macaque mml-mir-26a-2 (100% identical), pig ssc-mir-26a (100% identical), rat Mir26a-2 (100% identical), guinea pig MIR26A2 (98% identical), mouse Mir26a-2 (92% identical), tropical clawed frog xtr-mir-26-1 (80% identical), zebrafish dre-mir-26b (76% identical), dog MIR26A-2 (70% identical), zebrafish dre-mir-26a-1 (65% identical). Paralogues in human: MIR26A1 (63% identical), MIR26B (60% identical).